GP2 (glycoprotein 2)
Diseases named in the same sentence as GP2 in open-access papers (continued):
Sharing a sentence is not in itself a finding about the gene and the disease.
type 2 diabetes (5 papers, 2021 to 2026). "Recently, NUS1 and GP2 genes were reported to be associated with the risk of type 2 diabetes (T2D) in a Japanese population." (PMID 34326813, 2021). "Genetic variants in or near the CDKAL1, KLF9, GP2, ALDH2, and ITIH4 genes are associated with obesity and genetic variants in or near the GDAP1, PTF1A, SIX3, ALDH2, and PAX4 genes are specifically associated with type 2 diabetes in East Asians." (PMID 37749090, 2023).
celiac disease (4 papers, 2015 to 2024). An autoimmune genetic disorder with an unknown pattern of inheritance that primarily affects the digestive tract. "The reports of elevated GP2 IgA in patients with active celiac disease and particularly refractory variants thereof further support such assumption." (PMID 32178720, 2020). "Similar to celiac disease-specific IgA reactive with transglutaminase or deamidated gliadin, GP2 IgA levels were significantly reduced and eventually became negative after the initiation of a gluten-free diet as causal therapy." (PMID 32178720, 2020). "Recently, anti-GP2 antibodies have been detected in patients with active celiac disease (CD) and even refractory CD." (PMID 26047356, 2015). "A putative candidate could be the duodenal exocrine Brunner’s glands demonstrating a higher synthesis and probably secretion of GP2 in patients with Crohn’s and celiac disease." (PMID 39427219, 2024). "In a study involving 174 individuals with celiac disease and 84 patients on a gluten-free diet (GFD), significantly increased levels of anti-GP2 IgA were found and showed a strong association with levels of endomysial antibodies (EMA) and anti-tTG IgA antibodies." (PMID 38170255, 2024). "Importantly, when excluding patients with UC and celiac disease, the specificity of anti-GP2 autoantibodies for CD is approximately 98% compared to that for non-intestinal diseases." (PMID 38170255, 2024). "Furthermore, in patients with coexisting celiac disease, elevated levels of anti-GP2 IgA were observed, which correlated significantly with celiac disease-specific antibodies such as anti-tissue transglutaminase (anti-tTG) and anti-endomysial IgA antibodies." (PMID 38170255, 2024). "However, GP2 autoAb appears to be linked with the chronicity of inflammation as shown for the occurrence of GP2 IgA in celiac disease." (PMID 32178720, 2020). "Furthermore, patients with confirmed celiac disease also exhibit an autoimmune response to GP2." (PMID 38170255, 2024).
dyslipidemia (4 papers, 2020 to 2023). "Oral administration of GP2 in HFD-fed mice improves metabolic syndrome by modulating the intestinal FXR/GLP-1 axis." (PMID 32943612, 2020). "Our results suggest that GP2 has therapeutic potential for the treatment of metabolic syndrome." (PMID 32943612, 2020). "Conversely, increasing A2 glycan (GP2) and decreasing FA2G2 glycan (GP14) are consistent with the changing of certain IgG N-GPs which have been observed in association studies on chronic diseases, such as dyslipidemia (DL), SLE, RA, and chronic kidney disease (CKD)." (PMID 34804021, 2021). "To investigate the potential therapeutic effect of GP2 on metabolic syndrome, we gavaged HFD-fed mice with or without GP2 for 5 weeks." (PMID 32943612, 2020).
pancreatitis (4 papers, 2019 to 2021). Inflammation of the pancreas. "As GP2 is possibly involved in intraductal plug formation—an initial event of pancreatitis—after being secreted into the pancreatic duct, several previous studies attempted to identify both rare and common mutations in the GP2 gene associated with chronic pancreatitis." (PMID 34861888, 2021). "Further studies are needed to reveal the roles of GP2 and anti-GP2 autoantibodies in the context of the relationship between pancreatitis and CD." (PMID 33594081, 2021). "Interestingly, elevated serum GP2 levels were noted in patients with pancreatitis and in CD patients." (PMID 34064706, 2021). "Indeed, serum GP2 levels are increased in pancreatitis animal models and patients with CD68,69." (PMID 33594081, 2021).
pouchitis (4 papers, 2018 to 2024). Acute inflammation in the intestinal mucosa of the continent ileal reservoir (or pouch) in patients who have undergone ileostomy and restorative proctocolectomy (proctocolectomy, restorative). "Remarkably, GP2 autoAb occurrence could be linked with de novo CD in patients suffering from severe UC with pouchitis after colectomy and ileal pouch anal anastomosis (IPAA)." (PMID 32178720, 2020). "Furthermore, the association of loss of tolerance to GP2 with the appearance of de novo CD-like inflammation in patients with pouchitis supports the involvement of a disturbed interaction of GP2 with microbiota in the onset of CD." (PMID 32178720, 2020). "Even in UC cases, which generally have a reduced incidence of anti-GP2 autoantibodies, these antibodies can be detected in the serum and feces of patients who develop pouchitis after colectomy." (PMID 38170255, 2024). "Of note, dimeric GP2 IgA like most of the IgA secreted by mucosal plasma cells could be actively transported by epithelial cells onto mucosal surfaces as has been shown for GP2 IgA in pouchitis patients with de novo CD." (PMID 32178720, 2020).
Lassa fever (3 papers, 2008 to 2019). A viral hemorrhagic fever that is caused by the Lassa virus, which is transmitted by contact with infected rodents; it is characterized by fever, headache, malaise, myalgia, and hearing loss. "Thus, the development of native or quasi native recombinant LASV GP1 and GP2 as soluble, uncoupled proteins will improve current diagnostics, treatment, and prevention of Lassa fever." (PMID 19105844, 2008). "If proven true, NP may be the most relevant immunological marker for early detection of Lassa fever; whereas, a detectable immune response to GP1 and GP2 antigens may follow a more mature humoral response to infection." (PMID 18538016, 2008).
autoimmune liver disease (2 papers, 2020 to 2024). "Not surprisingly, the report of an association between GP2 IgA autoAbs and disease severity in patients with PSC gave a new impetus to autoAb research for autoimmune liver diseases." (PMID 32178720, 2020).
Autoimmunity (2 papers, 2021 to 2024). The occurrence of an immune reaction against the organism's own cells or tissues. "Therefore, the loss of tolerance to GP2 might be associated with the initiation and triggering of autoimmunity." (PMID 33594081, 2021). "It has been observed that untreated patients have higher levels of anti-GP2 autoantibodies than patients who have undergone treatment with probiotics, suggesting a potential role of microbial modulation in GP2-intolerant autoimmunity." (PMID 38170255, 2024). "Furthermore, studies have implicated the microbial composition and the presence of specific bacteria in the disruption of immune tolerance towards GP2 and the subsequent development of GP2-intolerant autoimmunity." (PMID 38170255, 2024).
cholangiocarcinoma (2 papers, 2021 to 2024). A carcinoma that arises from the intrahepatic biliary tree (intrahepatic cholangiocarcinoma) or from the junction, or adjacent to the junction, of the right and left hepatic ducts (hilar cholangiocarcinoma). "Further studies comparing anti-GP2 antibody titers in serum samples from independent cohorts of patients with PSC showed that anti-GP2 IgA autoantibodies were linked to a lower survival rate and an increased risk of developing cholangiocarcinoma, a type of bile duct cancer." (PMID 38170255, 2024). "The presence of anti-GP2 antibodies in individuals with PSC is associated with cholangiocarcinoma, increased mortality and reduced transplant free survival, indicating anti-GP2 antibodies might play a pathogenic role." (PMID 33936097, 2021).
Cirrhosis (2 papers, 2018). A chronic disorder of the liver in which liver tissue becomes scarred and is partially replaced by regenerative nodules and fibrotic tissue resulting in loss of liver function. "Consistently, anti-GP2 IgA predicted faster disease progression during follow-up, even after adjusting for the Mayo risk score or the presence of cirrhosis." (PMID 29321484, 2018). "There was an elevated occurrence of cirrhosis in anti-GP2 IgA-positive patients (35% vs. 11.1%, P = 0.022)." (PMID 29321484, 2018).
COVID-19 (2 papers, 2021). A disease caused by infection with severe acute respiratory syndrome coronavirus 2. "In COVID-19, plasmin seems to be of high relevance, as it may prime the SARS-CoV-2 glycoprotein 2, facilitating cell entry of viral particles." (PMID 34945736, 2021).
gestational diabetes (2 papers, 2021 to 2022). Carbohydrate intolerance first diagnosed during pregnancy. "Given the sharing of pathogenic contribution from genetic factors between T2D and gestational diabetes mellitus (GDM), we conducted the study to systematically examine the relationship of NUS1 and GP2 genes with the susceptibility to GDM in Chinese Han population." (PMID 34326813, 2021).
glioma (2 papers, 2013 to 2023). A benign or malignant brain and spinal cord tumor that arises from glial cells (astrocytes, oligodendrocytes, ependymal cells). "Our results indicate that alterations of eight out of eleven identified genes might have an important role in pathogenesis of glial tumors, while detected changes in GP2, KCNG2 and KIR3DL3 should be considered as passenger mutations, since these genes are not expressed in glial cells." (PMID 24358143, 2013). "We identified 8 plasma proteins which were increased in gliomas vs. meningiomas (GFAP, NEFL, EDDM3B, PROK1, MMP3, CTRL, GP2, SPINT3) and 4 proteins which were decreased in gliomas vs. meningiomas (FABP4, ALDH3A1, IL-12B and OXT)." (PMID 36959545, 2023). "For the other identified candidate biomarkers (EDDM3B, LMOD1, GP2, SPINT3, CTRL, OXT) there is no specific literature linking them to gliomas or other brain tumors." (PMID 36959545, 2023).
intestinal infection (2 papers, 2022). "Further studies are required to address whether GP2+ and GP2− CD103+CD11b+ cDC represent developmentally and functionally distinct cDC subsets, or different activation stages of the same subset as well as the importance of CD103+CD11b+ cDC‐derived GP2 in intestinal infection and inflammation." (PMID 37807915, 2022). "Importantly, however, our studies were performed on mice housed in pathogen‐free conditions and in non‐challenged situations, and it will be interesting in future studies to explore the role of cDC‐derived GP2 in models of intestinal infection and inflammation." (PMID 37807915, 2022). "Thus, pancreatic GP2 could control intestinal infections independently of the surface glycocalix composition of intestinal epithelial cells." (PMID 35020452, 2022).
Obesity (2 papers, 2017 to 2018). Accumulation of substantial excess body fat. "Five of the twenty-one obesity-dependent DEGs are associated with obesity and insulin resistance (MPHOSPH9, BRCA1, ASP, ALCAM, GP2)." (PMID 30305020, 2018). "Also, 4 of these DEGs have a known-role in placenta development and function (ALCAM, BRCA1 GP2, GSTA4) and 5 are associated with obesity and insulin resistance (MPHOSPH9, BRCA1, ASP, ALCAM, GP2)." (PMID 30305020, 2018). "In addition, despite our study being sufficiently powered, we failed to confirm the association with obesity for three novel identified adult BMI loci from East ancestry (KCNQ1-rs2237892, PAX6-rs652722 and GP2-rs12597579) in Chinese children." (PMID 29212175, 2017).
pancreatic diseases (2 papers, 2019 to 2021). "Furthermore, plasma GP2 levels were measured by the enzyme-linked immunosorbent assay (ELISA) in a clinical study involving patients with pancreatic diseases and control subjects." (PMID 34861888, 2021). "With the abundant expression of GP2 in pancreatic acinar cells, earlier studies focused on its role in pancreatic diseases." (PMID 34861888, 2021). "Although GP2 was initially found to be expressed almost exclusively in the pancreas, its roles in the pathogenesis of pancreatic diseases are largely unknown." (PMID 34861888, 2021).
Parkinson disease (2 papers, 2019 to 2026). A progressive degenerative disorder of the central nervous system characterized by loss of dopamine producing neurons in the substantia nigra and the presence of Lewy bodies in the substantia nigra and locus coeruleus. "GP2's unified framework supports equitable recruitment for gene-targeted therapeutic studies and helps address critical gaps in Parkinson's disease genetics and future therapeutic development." (PMID 42051573, 2026). "B. Representation of the opposite situation where GP1 genes are disfavored and GP2 are favored by the codon employment, as in Parkinson’s disease." (PMID 31288782, 2019).
prostate carcinoma (2 papers, 2024 to 2025). A carcinoma that arises from epithelial cells of the prostate gland. "Thirdly, we picked GP2, an immune-associated gene, that also has been shown to be transcriptionally upregulated in prostate cancer with loss of PTEN expression in a prior screening study." (PMID 39653828, 2025). "Three proteins were associated with risk of prostate cancer: GP2, TSPAN1, and FLT3LG [1.29 (1.21–1.36), 1.14 (1.09–1.18), and 0.87 (0.82–0.92)] and three were associated with endometrial cancer: CHRDL2, KLK4, and WFIKKN1 [1.42 (1.21–1.65), 1.41 (1.20–1.65), and 1.42 (1.20–1.68)]." (PMID 38750076, 2024).
teratoma (2 papers, 2022 to 2025). A non-seminomatous germ cell tumor characterized by the presence of various tissues which correspond to the different germinal layers (endoderm, mesoderm, and ectoderm). "Their results showed teratoma/outgrowth rates of non-sorted (NS) 27% (4/15), FT 18% (3/17) and 0% (0/11) in GP2-enriched pancreatic progenitors, demonstrating that targeted purification has the potential to eliminate teratoma formation." (PMID 41226304, 2025).
urinary tract infection (2 papers, 2022 to 2025). "Glycoprotein 2 (GP2) filaments protect against gastrointestinal and urinary tract infections by acting as decoys for the bacterial lectin FimH." (PMID 40550004, 2025). "Glycoprotein 2 (GP2) and uromodulin (UMOD) filaments protect against gastrointestinal and urinary tract infections by acting as decoys for bacterial fimbrial lectin FimH." (PMID 35273390, 2022).
acute renal failure (1 paper, 2025). "In Gp2, 7 participants (3.9%) had tuberculosis, 4 (2.2%) had AIDS-defining conditions, 3 (1.7%) died (1 from TB, 1 from acute renal failure, and 1 unknown cause), and 1 (0.6%) each had cancer and immune reconstitution inflammatory syndrome." (PMID 40630936, 2025).
autoimmune disease (1 paper, 2024). A disorder resulting from loss of function or tissue destruction of an organ or multiple organs, arising from humoral or cellular immune responses of the individual to their own tissue constituents. "These exciting research findings provide a promising glimpse into the future of GP2’s therapeutic potential, successfully demonstrating the prospects of targeting GP2 in the treatment of autoimmune diseases and gastrointestinal disorders." (PMID 38170255, 2024).
bile duct diseases (1 paper, 2018). "Third, in that study anti-GP2 IgA positivity was not exclusively associated with PSC, but rather with the presence of large bile duct diseases, irrespectively of their malignant or benign character based on findings in their disease control groups." (PMID 29321484, 2018).
chorioretinal (1 paper, 2024). "On Optos imaging, there was chorioretinal atrophy and bone spicule pigmentation in the periphery for GP2-81 as well as a hyper-autofluorescence signal within the macula." (PMID 39858579, 2024).
chronic obstructive pulmonary disease (1 paper, 2021). A chronic and progressive lung disorder characterized by the loss of elasticity of the bronchial tree and the air sacs, destruction of the air sacs wall, thickening of the bronchial wall, and mucous accumulation in the bronchial tree. "Losmapimod, an p38 MAPK inhibitor, was developed as a therapeutic drug for chronic obstructive pulmonary disease (COPD) and has been reported to inhibit LASV entry by blocking the pH-dependent GP2-mediated fusion without requiring inhibition of p38 MAPK." (PMID 34206216, 2021).
colonic disease (1 paper, 2024). "Positive anti-GP2 autoantibodies have been linked to distinct patient characteristics, including an earlier onset, lower incidence of isolated colonic disease, and higher incidence of stenotic behavior anti-GP2 autoantibodies negative ones." (PMID 38170255, 2024).
cystic fibrosis (1 paper, 2025). Autosomal recessive disorder caused by pathogenic variants in the CFTR gene (cystic fibrosis transmembrane conductance regulator), which encodes a chloride and bicarbonate channel expressed in epithelial cells, and follow the diagnosis criteria. "This revealed an additional 67 significantly differentially expressed protein groups between cystic fibrosis patients and healthy individuals, including GUCA2A, ADAMDEC1, and FABP1 (upregulated) and GP2 (downregulated)." (PMID 40425748, 2025).
Dystonia (1 paper, 2025). An abnormally increased muscular tone that causes fixed abnormal postures. "We screened sequencing data from 15,738 individuals (7,851 PD, 4,287 atypical parkinsonism, and 3,600 unaffected) from GP2 and AMP-PD for variants in genes linked to isolated dystonia, dystonia-parkinsonism, and myoclonus-dystonia." (PMID 40672488, 2025).
E. coli infection (1 paper, 2022). "Our findings suggest that GP2 plays a role in the defense against E. coli infection and in the corresponding host immune response." (PMID 35020452, 2022).
Ebola (1 paper, 2015). "The most efficacious mAbs in this panel were found to recognize a novel “wing” feature on the GP2 subunit that is unique to Marburg and does not exist in Ebola." (PMID 26115029, 2015).
emphysema (1 paper, 2019). "M cells marked with GP2 or Spi-B were observed in pathologically induced elastase-induced and tobacco smoking-induced emphysema models or in an LPS-induced pulmonary inflammation model, respectively." (PMID 31244859, 2019).
endometriosis (1 paper, 2024). The growth of functional endometrial tissue in anatomic sites outside the uterine body. "Interestingly, N-glycome correlates with the microbes specific for endometriosis Anaerococcus senegalensis, namely, core fucosylated mono-antennary glycans (GP2) from IgG and trigalactosylated and triantennary glycans from serum." (PMID 39455640, 2024).
epilepsy (1 paper, 2022). A brain disorder characterized by episodes of abnormally increased neuronal discharge resulting in transient episodes of sensory or motor neurological dysfunction, or psychic dysfunction. "In this study, five bisecting GlcNAc glycans (GP1, GP2, GP3, GP4, and BN) were higher in the epilepsy patients." (PMID 35845609, 2022).
gallstones (1 paper, 2020). Solid crystalline precipitates in the biliary tract, usually formed in the gallbladder, resulting in the condition of cholelithiasis. "Given the significant correlation of loss of mucosal tolerance to GP2 to the pathophysiology of obstructive fibrotic changes in the biliary tract, the presence of GP2 in bile and its participation in gallstone formation would support a pathogenic role of GP2 IgA." (PMID 32178720, 2020).
gastric cancer (1 paper, 2021). A primary or metastatic malignant neoplasm involving the stomach. "Haptoglobin glycosylation in clinical samples consisting of healthy controls (n = 47) and gastric cancer patients (n = 43) was extensively investigated using three groups of tryptic glycopeptides: GP1 (including Asn184), GP2 (including Asn207 and Asn211), and GP3 (including Asn241)." (PMID 34207451, 2021).
liver cancer (1 paper, 2022). An epithelial or non-epithelial malignant neoplasm that arises from the liver. "In fact, Gp2’s oncogene disruption has been widely cited as one of the many broken checkpoints leading to liver cancer." (PMID 36301997, 2022).